OLFML2A (olfactomedin like 2A)
Synonyms: FLJ00237; PRO34319
Tractability: Antibody: UniProt places it where antibodies can reach, with medium confidence; UniProt predicts a signal peptide or a membrane-spanning region; its Gene Ontology location is reachable by antibodies, with medium confidence.
Gene: Protein-coding gene on chromosome 9 (124,777,122 to 124,814,885, forward strand). Ensembl gene ENSG00000185585.
Subcellular location: Secreted
Subcellular location (Human Protein Atlas): Nucleoplasm; Vesicles; Golgi apparatus; Predicted to be secreted
Gene Ontology:
Molecular function: extracellular matrix binding; identical protein binding
Biological process: signal transduction
Cellular component: extracellular region; extracellular matrix
Genetic constraint (gnomAD): Loss-of-function variants: 45 observed, 57.13 expected, observed/expected ratio (o/e) 0.79, 90% interval 0.62 to 1.01. The upper end of that interval is the gene's LOEUF score, 1.01, which puts it in group 4 of 6, group 1 being the genes least tolerant of losing a copy. Missense variants: 848 observed, 834.99 expected, observed/expected ratio (o/e) 1.02, 90% interval 0.96 to 1.08. Synonymous variants: 344 observed, 356 expected, observed/expected ratio (o/e) 0.97, 90% interval 0.88 to 1.06.
Homologues: Orthologues: chimpanzee OLFML2A (99% identical), macaque OLFML2A (97% identical), pig OLFML2A (88% identical), dog OLFML2A (86% identical), rabbit OLFML2A (85% identical), mouse Olfml2a (83% identical), rat Olfml2a (82% identical), guinea pig OLFML2A (78% identical), tropical clawed frog olfml2a (63% identical), zebrafish olfml2a (61% identical), zebrafish OLFML2A (31% identical). Paralogues in human: OLFML2B (46% identical), MYOC (20% identical), OLFM2 (20% identical), OLFM1 (19% identical), OLFM3 (18% identical), OLFM4 (17% identical), OLFML3 (15% identical), GLDN (15% identical), OLFML1 (14% identical).
Diseases named in the same sentence as OLFML2A in open-access papers:
OLFML2A is named in the same sentence as 10 diseases in open-access papers, as found by Europe PMC text mining. Sharing a sentence is not in itself a finding about the gene and the disease. The quoted sentences say what the papers report.
glioma (4 papers, 2021 to 2026). A benign or malignant brain and spinal cord tumor that arises from glial cells (astrocytes, oligodendrocytes, ependymal cells). "Collectively, these findings confirmed the TCGA analysis results and suggested a potential association between OLFML2A upregulation and the progression of glioma." (PMID 34650914, 2021). "However, the molecular function of OLFML2A and its underlying mechanism of action in glioma remain unclear." (PMID 34650914, 2021). "The functional significance of this axis was further confirmed in vivo, where OLFML2A knockdown suppressed tumor growth in both subcutaneous and intracranial glioma xenograft models by impairing Wnt/β-catenin-dependent proliferatio." (PMID 41607539, 2026). "In this study, we found that OLFML2A expression was significantly upregulated in glioma specimens and positively correlated with pathological grades in glioma patients." (PMID 34650914, 2021). "By analyzing datasets from The Cancer Genome Atlas (TCGA), we observed that OLFML2A expression was significantly upregulated in glioma tissues compared to normal brain tissue and that OLFML2A expression was positively correlated with glioma grades." (PMID 34650914, 2021). "Our results indicated that OLFML2A is upregulated in glioma, positively correlated with tumor grade, and negatively correlated with the prognosis of glioma patients." (PMID 34650914, 2021). "Downregulation of OLFML2A expression dramatically suppressed the growth of glioma cells both in vitro and in vivo, and silencing OLFML2A significantly promoted the apoptosis of glioma cells." (PMID 34650914, 2021). "Real-time PCR results showed that OLFML2A expression was upregulated in four different glioma cell lines." (PMID 34650914, 2021). "Collectively, these findings provided a strong rationale for the role of OLFML2A as a crucial molecule that regulates the proliferation of glioma cells." (PMID 34650914, 2021). "Consistent with previous studies, our results indicate that OLFML2A acts as an oncogene that exerts an important effect on glioma progression." (PMID 34650914, 2021). "In summary, our results suggest that OLFML2A plays a crucial role in the proliferation of glioma and acts as an oncogene to promote the progression of glioma in humans." (PMID 34650914, 2021). "In the present study, we first analyzed an available genomic database (TCGA) and identified OLFML2A as a putative molecule involved in glioma tumorigenesis." (PMID 34650914, 2021). "The results of an IPA-based interaction network analysis confirmed that APP is an important intermediate molecule that mediates the downstream regulatory effects of OLFML2A in glioma." (PMID 34650914, 2021). "To assess the biological role of OLFML2A in glioma, we used a lentivirus-based shRNA strategy to knockdown OLFML2A expression in glioma cell lines." (PMID 34650914, 2021). "By uncovering the oncogenic effects in human and rodent gliomas, our data support OLFML2A as a potential therapeutic target for glioma." (PMID 34650914, 2021). "Kaplan–Meier survival analysis of TCGA data revealed that glioma patients with higher OLFML2A expression had shorter overall survival." (PMID 34650914, 2021). "OLFML2A knockdown has been shown to suppress proliferation and induce apoptosis in glioma cells." (PMID 41607539, 2026). "Knockdown of Olfml2a in glioma cells could promote apoptosis and inhibit the Wnt/β-catenin signalling pathway." (PMID 37670341, 2023). "Our data indicate that the oncogenic effect of OLFML2A in glioma occurs through regulation of Wnt/β-catenin signaling, which may provide a new potential therapeutic target for glioma." (PMID 34650914, 2021). "Finally, we demonstrated that APP is an important intermediate molecule that mediates the downstream regulatory effects of OLFML2A in glioma." (PMID 34650914, 2021). "Furthermore, we confirmed that Wnt/β-catenin pathway activation is involved in OLFML2A-regulated glioma cell proliferation in vitro and in vivo." (PMID 34650914, 2021).
glioma (continued). "Taken together, these findings suggested that OLFML2A is overexpressed in human glioma." (PMID 34650914, 2021). "Furthermore, OLFML2A downregulation suppressed the growth of transplanted glioma subcutaneously and intracranially by inhibiting Wnt/β-catenin pathway-dependent cell proliferation." (PMID 34650914, 2021). "As expected, OLFML2A was significantly upregulated in glioma tissues." (PMID 34650914, 2021). "In addition, we observed that the level of OLFML2A is correlated with glioma proliferation and apoptosis." (PMID 34650914, 2021). "A positive correlation between OLFML2A expression and glioma pathological grades suggested that OLFML2A may be involved in the development and progression of glioma." (PMID 34650914, 2021). "Moreover, Kaplan–Meier survival analysis of TCGA data revealed that glioma patients with higher OLFML2A expression had shorter overall survival." (PMID 34650914, 2021). "To further investigate whether OLFML2A promotes glioma cell proliferation by regulating cell apoptosis, we used Annexin-V staining to assess apoptosis in OLFML2A-knockdown and control U251 cells." (PMID 34650914, 2021). "Therefore, to better understand the function of OLFML2A and identify new markers for targeted glioma therapy, in vitro and in vivo assays and bioinformatics analyses were performed to elucidate the function and mechanisms of OLFML2A in glioma progression." (PMID 34650914, 2021). "However, the mechanisms underlying OLFML2A-mediated glioma development and its downstream pathways have not been systematically explored." (PMID 34650914, 2021). "Furthermore, OLFML2A levels were positively correlated with pathological grades in glioma patients." (PMID 34650914, 2021). "Importantly, OLFML2A knockdown in glioma cells inhibited cell proliferation and promoted apoptosis." (PMID 34650914, 2021). "Similarly, gross observations also showed that OLFML2A downregulation could significantly suppress orthotopic glioma growth, and the positive rate of Ki-67 was also decreased after OLFML2A knockdown." (PMID 34650914, 2021). "Importantly, OLFML2A may be a promising target gene for glioma treatment." (PMID 34650914, 2021). "In contrast, minimal to no OLFML2A expression was detected in cancers such as lymphoma and glioma." (PMID 41607539, 2026). "Moreover, the role of OLFML2A in glioma has not been reported." (PMID 34650914, 2021).
triple-negative breast carcinoma (2 papers, 2026). An invasive breast carcinoma which is negative for expression of estrogen receptor (ER), progesterone receptor (PR), and human epidermal growth factor receptor 2 (HER2). "To elucidate the biological function of OLFML2A in triple-negative breast cancer cells, we engineered MDA-MB-231 cell line variants with either knockout (KO) or overexpression (OE) of OLFML2A." (PMID 41607539, 2026). "Collectively, these results establish EZH2 as a downstream interacting partner of OLFML2A and suggest that its expression is positively regulated by OLFML2A in triple-negative breast cancer (TNBC) cells." (PMID 41607539, 2026). "This study underscores the potential of OLFML2A as a therapeutic target for triple-negative breast cancer; however, several limitations must be acknowledged." (PMID 41607539, 2026). "To elucidate the role of OLFML2A in the regulation of the tumor cell cycle in vivo, we developed a xenograft model of triple-negative breast cancer in mice." (PMID 41607539, 2026). "OLFML2A acts as an oncogenic gene in triple-negative breast cancer." (PMID 41607539, 2026). "Our findings suggest that OLFML2A may facilitate cell cycle progression by regulating EZH2, implicating it as a potential therapeutic target for triple-negative breast cancer." (PMID 41607539, 2026).
breast carcinoma (1 paper, 2023). "In a previous study, researchers found that the presence of OLFML2A in breast cancer cells could hinder the development and metastasis of cancer cells." (PMID 36873740, 2023).
glioblastoma (1 paper, 2021). The most malignant astrocytic tumor (WHO grade IV). "Overall, OLFML2A was shown to primarily regulate glioblastoma through Wnt/β-catenin signaling by targeting APP." (PMID 34650914, 2021). "Our results suggested that OLFML2A promotes the progression of glioblastoma and may be a potential novel prognostic factor for glioblastoma." (PMID 34650914, 2021).
keloid (1 paper, 2025). An irregularly shaped, elevated mark on the skin caused by deposits of excessive amounts of collagen during wound healing. "We then focused on comparing the expression differences of IGFBP2+ fib marker genes (IGFBP2, FGFBP2, OLFML2A, CPE, APOD, SLC7A2) between keloids and normal controls." (PMID 39902627, 2025). "IGFBP2+ fibs are distinguished by the expression of marker genes including IGFBP2, FGFBP2, OLFML2A, CPE, APOD, and SLC7A2, which are markedly upregulated in normal skin tissue relative to keloid tissue." (PMID 39902627, 2025).
leukemia (1 paper, 2021). A malignant (clonal) hematologic disorder, involving hematopoietic stem cells and characterized by the presence of primitive or atypical myeloid or lymphoid cells in the bone marrow and the blood. "OLFML2A expression was shown to be negatively correlated with the biological progression and clinical features of TNBC, LIHC, and leukemia." (PMID 34650914, 2021).
pterygium (1 paper, 2021). A wedge-shaped fibrovascular lesion arising from the bulbar conjunctiva and extending to the cornea. "Using GEO databases, we also identified five hub genes (DSP, MXRA5, ARHGAP35, TMEM43, and OLFML2A) that were most correlated with the development of pterygium." (PMID 34249924, 2021). "After analyzing the differentially methylated m6A peaks and synchronously differentially expressed genes, we searched the Gene Expression Omnibus database and identified five genes related to the development of pterygium (DSP, MXRA5, ARHGAP35, TMEM43, and OLFML2A)." (PMID 34249924, 2021).
cancer (4 papers, 2021 to 2026). A tumor composed of atypical neoplastic, often pleomorphic cells that invade other tissues. "To detect the differential expression of OLFML2A, we first investigated OLFML2A gene expression in 33 human cancers in TCGA using the TIMER database." (PMID 36873740, 2023). "From The Cancer Genome Atlas, researchers used the data of OLFML2A gene to analyze and study the pan-cancer using R language and then divided the high and low levels of this protein into two groups to study its relationship with the clinical characteristics of the disease." (PMID 36873740, 2023). "In total, nine inflammation and cancer-associated DEGs were selected to show their changed expression patterns, comprising four up-DEGs (ADM, FSTL3, SPDEF, and SPNS2) and five down-DEGs (TACSTD2, CCL2, EDIL3, FAM20C, and OLFML2A)." (PMID 37953789, 2023). "According to the pan-cancer analysis, OLFML2A was differentially expressed in different tumors." (PMID 36873740, 2023). "Immunohistochemistry results using the antibody HPA021180 revealed that OLFML2A exhibits a cancer type-specific expression profile, with notably high cytoplasmic staining in several solid malignancies." (PMID 41607539, 2026).
tumor (4 papers, 2021 to 2026). "By clarifying the role of OLFML2A in promoting tumor progression, particularly through cell cycle modulation, we seek to identify novel therapeutic targets for TNBC." (PMID 41607539, 2026). "Secondly, While our in vitro and in vivo findings support the tumor-promoting roles of OLFML2A and EZH2 in TNBC progression, future large-scale clinical studies are needed to definitively correlate their expression with patient outcomes." (PMID 41607539, 2026). "Compared to the control group (C-OE), the knockout of OLFML2A resulted in significantly slower tumor growth and reduced final tumor volume, whereas overexpression of OLFML2A led to accelerated tumor progression and increased tumor sizes." (PMID 41607539, 2026). "This research aims to identify molecular targets that interact with OLFML2A and to elucidate the mechanisms by which it influences the tumor cell cycle." (PMID 41607539, 2026). "RNA levels of potential target genes IGF1R, NOTCH3 and OLFML2A were increased in 3D tumor spheroid culture compared to cells grown in 2-D culture to normal, ∼70% confluence." (PMID 38109320, 2024). "U87MG cells infected with Scr-shRNA or OLFML2A-shRNA were transplanted into the right flanks of immunocompromised nude mice, and the results showed that OLFML2A knockdown led to significant decreases in tumor volume and weight (n = 10)." (PMID 34650914, 2021). "Firstly, although we have demonstrated through various experimental approaches that OLFML2A influences tumor cell cycle progression and suppresses apoptosis via the regulation of EZH2, the upstream regulatory networks and detailed molecular mechanisms remain insufficiently understood." (PMID 41607539, 2026). "We used a xenograft model to verify whether OLFML2A knockdown reduces tumor growth in vivo." (PMID 34650914, 2021). "The silencing of OLFML2A markedly reduced the proliferation of MDA-MB-231 cells, induced cell cycle arrest at the G1 phase, and inhibited tumor growth." (PMID 41607539, 2026). "The qPCR analysis quantitatively confirmed the upregulation of MFSD5, PARVA, PRSS3, OLFML2A, and NOTCH3 at the mRNA level in tumor tissues, with statistically significant differences compared to adjacent tissues." (PMID 40781483, 2025). "Collectively, these data suggest that OLFML2A plays a critical role in promoting cell proliferation and inhibiting apoptosis in MDA-MB-231 cells, underscoring its potential significance in sustaining tumor cell viability." (PMID 41607539, 2026).
OLFML2A also shares sentences with these, for which no sentence is quoted: lymphoma (1 paper).